BANF2 (BANF family member 2)
Description:
May play a role in BANF1 regulation and influence tissue-specific roles of BANF1.
Synonyms: BAF-L; BAFL; C20orf179; dJ803K15.1; BAF2
Tractability: No criterion of Open Targets' tractability assessment is met for any kind of drug.
Gene: Protein-coding gene on chromosome 20 (17,693,672 to 17,735,871, forward strand). Ensembl gene ENSG00000125888.
Subcellular location: Nucleus; Cytoplasm
Gene Ontology:
Molecular function: DNA binding
Biological process: chromosome organization
Cellular component: nucleus; condensed chromosome; cytoplasm
Genetic constraint (gnomAD): Loss-of-function variants: 6 observed, 10.02 expected, observed/expected ratio (o/e) 0.6, 90% interval 0.33 to 1.18. The upper end of that interval is the gene's LOEUF score, 1.18, which puts it in group 5 of 6, group 1 being the genes least tolerant of losing a copy. Missense variants: 96 observed, 112.22 expected, observed/expected ratio (o/e) 0.86, 90% interval 0.72 to 1.01. Synonymous variants: 50 observed, 42.8 expected, observed/expected ratio (o/e) 1.17, 90% interval 0.93 to 1.48.
Homologues: Orthologues: chimpanzee BANF2 (98% identical), macaque BANF2 (96% identical), dog BANF2 (90% identical), rat Banf2 (89% identical), mouse Banf2 (88% identical), pig BANF2 (87% identical), guinea pig BANF2 (81% identical), rabbit BANF2 (79% identical). Paralogues in human: BANF1 (40% identical).
Diseases named in the same sentence as BANF2 in open-access papers:
BANF2 is named in the same sentence as 5 diseases in open-access papers, as found by Europe PMC text mining. Sharing a sentence is not in itself a finding about the gene and the disease.
BANF2 shares sentences with these, for which no sentence is quoted: male infertility (2 papers); amyotrophic lateral sclerosis (1); asthenozoospermia (1); Crohn disease (1); inflammatory bowel disease (1).